HGF (hepatocyte growth factor)
Diseases named in the same sentence as HGF in open-access papers (continued):
Sharing a sentence is not in itself a finding about the gene and the disease.
periodontitis (continued). "HGF is significantly higher in both GCF and saliva from periodontitis patients compared to healthy individuals, potentially correlating with disease severity." (PMID 34128105, 2021). "For discriminating health vs periodontitis groups, the predictor variables resulting from the CART analysis included HGF, MMP-9, LBP and IL-1b." (PMID 33742017, 2021). "The levels of hepatocyte Growth Factor (HGF), a multifunctional cytokine, were found to positively correlate with periodontitis progression and smoking habits." (PMID 31890650, 2019). "Hepatocyte growth factor (HGF), a pluripotent, ubiquitous, and mostly regenerative cytokine, is strongly involved in the pathogenesis and progression of periodontitis." (PMID 25389376, 2014). "Within the limitations of the study, the estimation of HGF in saliva and GCF can be used as a marker of active periodontitis." (PMID 25389376, 2014). "We also observed that HGF significantly altered the abundance of some bacterial taxa in mice without periodontitis, suggesting HGF still plays a momentous role in the gut microbiota even in the absence of periodontitis." (PMID 40427685, 2025). "These cells do not exist in homeostasis but are detected in periodontitis identifying HGF/Met as a key macrophage regulatory pathway." (PMID 36193890, 2022). "Nevertheless, even when TIMP-1 levels were > 89.27 ng/ml and HGF concentration were higher than 2.753 pg/ml, no further splits were made and the accuracy of determining periodontitis patients was as high as 94.1%." (PMID 33742017, 2021). "The plotted ROC curves showed a good predictor value of the MMP-9/TIMP-1 ratio, (MMP-8 + MMP-9)/TIMP-1 ratio, and HGF (as top three), followed by the MMP-9, MMP-2, MMP-8 + MMP-9 sum and the MMP-8/TIMP-1 ratio, for differentiation of periodontitis versus health conditions (AUC ≥ 0.95)." (PMID 33742017, 2021). "An antibody-based anti-HGF approach resulted in an inhibition of collagen gel degradation in this in vitro model, suggesting HGF signaling being crucially involved in ECM turnover, and antagonism of HGF representing a valid treatment approach to ameliorate periodontitis." (PMID 34128105, 2021). "When HGF was higher than this concentration, then TIMP-1 at levels lower than 89.27 ng/ml could achieve increased identification of periodontitis cases to an accuracy of 97.2% with one false positive." (PMID 33742017, 2021). "The plotted ROC curves showed a good predictor value for the MMP-9/TIMP-1 ratio, the (MMP-8 + MMP-9)/TIMP-1 ratio and the MMP-8 + MMP-9 sum (as top three), followed by the MMP-8/TIMP-1 ratio, HGF, MMP-2, and OPG for differentiation of periodontitis versus gingivitis conditions (AUC ≥ 0.85)." (PMID 33742017, 2021). "The elevated levels of HGF in the saliva and GCF in the study population could explain the intrinsic mechanism triggering the severity of the periodontitis in smokers." (PMID 25389376, 2014). "The salivary HGF was compared among the healthy, never-smoker with periodontitis, and smoker with periodontitis groups." (PMID 25389376, 2014). "In the present study, a significantly higher level of salivary HGF was found in smokers with periodontitis and nonsmokers with periodontitis compared to the control group." (PMID 25389376, 2014). "The smoker with periodontitis group had significantly higher levels (P < 0.01) of salivary hepatocyte growth factor than the healthy and never-smoker with periodontitis groups." (PMID 25389376, 2014). "Regarding the microbial barrier, the 16S rRNA sequencing showed that HGF contributed to a discrepancy in the intestinal microbiota based on α-diversity and β-diversity whether or not periodontitis was present." (PMID 40427685, 2025). "Interestingly, results showed an up-regulation of colony-stimulating factor-1 (CSF-1), S100A8/A9, S100A12, interleukin (IL)-1β, matrix metalloproteinase (MMP)-8, and hepatocyte growth factor (HGF), in patients with periodontitis with a statistical significance of p<0.001." (PMID 37224160, 2023).
periodontitis (continued). "The exact role of HGF in the course of periodontitis is not yet clear." (PMID 35408871, 2022). "The observations from the current study reveal that the estimation of HGF in the crevicular fluid and saliva could serve as a noninvasive indicator of periodontitis." (PMID 25389376, 2014). "However, no studies have investigated whether HGF exacerbates periodontitis-induced gut dysbiosis—a critical gap in understanding oral–gut axis pathogenesis." (PMID 40427685, 2025). "Notably, we observed the selective downregulation of occludin but not ZO-1 in HGF-Tg mice, suggesting that HGF may preferentially target specific TJ components during periodontitis." (PMID 40427685, 2025). "Interestingly, the NMDS plot also illustrated that the microbial communities in the HGF-Tg mice clustered separately from those in the WT mice whether or not periodontitis was present." (PMID 40427685, 2025). "Hence, in the present study, the saliva and gingival crevicular fluid HGF levels were estimated to assess periodontal disease activity in smokers and to compare these levels with those present in a nonsmoking group of patients with periodontitis." (PMID 25389376, 2014). "We identified the CHEMERIN, HGF, IFN-I, IL16, LIFR, and APELIN pathways as not being active during homeostasis but rather, to be active in periodontitis." (PMID 36193890, 2022). "The objective of the study was to estimate the level of HGF in saliva and gingival crevicular fluid (GCF) in smokers with periodontitis and to compare these levels with that of nonsmokers with periodontitis and healthy controls." (PMID 25389376, 2014). "The HGF levels were found to be significantly high in the saliva and GCF of smokers with periodontitis compared to both never-smokers with periodontitis and the healthy control group." (PMID 25389376, 2014). "The HGF levels in the GCF also showed a similar pattern, with the highest levels in smokers (3367.86 ± 897.34), followed by nonsmoking subjects with periodontitis (2823.33 ± 733.76) and healthy subjects (1860.00 ± 643.59)." (PMID 25389376, 2014). "However, although stimuli with periodontal characteristics were used here to simulate a periodontitis condition, this does not properly model a chronic disease situation in vivo and can only help to investigate the regulation of CYP27B1 in hGF and hPDLC." (PMID 22761920, 2012). "It should be considered, however, that although stimuli with periodontal characteristics were used to simulate a periodontitis-like condition, this does not properly model the chronic disease situation in vivo, and can only help to investigate the regulation of CYP27A1 in hGF and hPDLC." (PMID 23251684, 2012). "Since cell sheet transplanting requires open flap surgery, which may be traumatic for patients, DPSC injection with or without HGF transfection should be considered as an effective non-surgical therapy; DPSC sheets are an appropriate surgical therapy for periodontitis." (PMID 26670567, 2015).
renal carcinoma (20 papers, 2011 to 2025). A carcinoma arising from the epithelium of the renal parenchyma or the renal pelvis. "Cabozantinib inhibits HGF-induced PD-L1 expression in renal cancer cell-injected mouse models, indicating that it can prevent tumor cell immune escape through HGF/c-MET signaling." (PMID 38289361, 2024). "In summary, the HGF/c‐Met signaling pathway plays a pivotal role in the initiation and progression of renal cancer." (PMID 39092291, 2024). "VHL gene mutations and hypoxic conditions can lead to the upregulation of HGF and its receptor c‐Met in renal cancer." (PMID 39092291, 2024). "HGF was shown to increase expression of CCL20 in neurons, while in cancer, HGF stimulation induced CCL20 secretion in papillary carcinoma of the thyroid and inhibition of HGF resulted in lower CCL20 levels in a renal cancer model." (PMID 34853656, 2021). "This HGF-independent CDCP1-Met interaction was also observed in the renal cancer cell lines, A498 and ACHN, in which endogenous CDCP1 and Met are up-regulated." (PMID 33574034, 2021). "The treatment with the c-Met ligand, Hepatocyte Growth Factor (HGF) (a known inducer of the tumor-promoting pathways in renal cancer), also increased Akt phosphorylation." (PMID 32635337, 2020). "We wanted to study if RAPA and Honokiol combination can restrict c-Met-induced renal cancer cell growth following treatment with the c-Met ligand HGF." (PMID 32635337, 2020). "Next, we studied the effect of Honokiol (HNK) on HGF-induced Akt phosphorylation in renal cancer cells; and how is it altered in the presence of RAPA." (PMID 32635337, 2020). "In renal cancer cells, it has been shown that stimulation with HGF increases PD-L1 levels via the MAP kinase pathway." (PMID 33233528, 2020). "We also found that HNK significantly inhibited the expression of basal as well as HGF-induced GTP-bound active Ras in renal cancer cells compared with vehicle-treated control." (PMID 28724911, 2017). "Our recent report suggests that HGF/c-Met-mediated signaling promotes Ras activation in renal cancer cells." (PMID 28724911, 2017). "Here, we found that in the presence of CsA treatment, HGF-induced Ras activation was further increased; and we also noted that CsA moderately induced the basal c-Met phosphorylation in renal cancer cells compared with vehicle-treated control." (PMID 28724911, 2017). "By MTT assay, we observed that HNK treatment significantly inhibited HGF/c-Met-induced proliferation of renal cancer cells." (PMID 28724911, 2017). "Additionally, a study on renal cancer revealed that HGF/c-Met enhances the level of nuclear factor E2-related factor 2 (Nrf2), thereby alleviating oxidative stress and apoptosis, both in vitro and in vivo." (PMID 40564462, 2025). "Future research should further elucidate the molecular mechanisms underpinning the role of the HGF/c‐Met pathway in renal cancer initiation and progression and explore safer and more effective c‐Met inhibitors, ultimately providing innovative strategies for the precision treatment of renal cancer." (PMID 39092291, 2024). "Additionally, other signaling pathways, such as the Wnt/β‐catenin, cAMP, and hepatocyte growth factor (HGF)/c‐Met pathways, also contribute to the malignant progression of renal cancer." (PMID 39092291, 2024). "However, RAPA + Honokiol combination treatment markedly increased renal cancer cell apoptosis even in the presence of HGF." (PMID 32635337, 2020). "Through annexin V and propidium iodide staining, and by analyzing the cellular apoptotic index through flow cytometry, we observed that HGF treatment protected renal cancer cells from apoptosis, whereas HNK significantly increased cell death in both HGF-treated and control cells." (PMID 28724911, 2017).
renal carcinoma (continued). "Our findings also suggest that CNI (CsA), which is used for the treatment of immune disorders, enhances c-Met activation and augments HGF/c-Met-induced Ras activation in renal cancer cells; and that HNK treatment down-regulates c-Met activation to inhibit CNI-induced renal tumor growth." (PMID 28724911, 2017). "Here, we examined how the CsA- and HGF-treated renal cancer cells can increase the ability of endothelial cells (HUVEC) to form tube-like structures (tube formation assay), an important step in the cascade of events that leads to new vessel formation; and if HNK can block the process." (PMID 28724911, 2017). "For example, in PC12 cells, RanBPM modulates BDNF-induced neuronal morphogenesis by regulating TrkB activation of MAPK and Akt, and, in human renal carcinoma cells, RanBPM enhances HGF-induced cell migration by interacting with Met and promoting GTP-Ras association and Erk phosphorylation." (PMID 27835883, 2016). "In addition, when renal carcinoma cells were mixed with EVs and subcutaneously injected in mice, the authors observed an up-regulation of hepatocyte growth factor (HGF) expression, at the mRNA and protein levels." (PMID 25157253, 2014). "However, some additional apoptotic/anti-apoptotic factors (Bax, Fas ligand and the inhibitor of apoptosis family members, IAPs) may also be involved in HGF-mediated survival of sorafenib-treated renal cancer cells." (PMID 30647407, 2019). "It was also reported that after the stimulation of the HGF/MET signaling pathway, renal cancer cells exhibited the up-regulation of PD-L1 expression through the PI3K pathway." (PMID 40330151, 2025). "In fact, hepatocyte growth factor (HGF) and its receptor, c-Met, whose levels are increased at GD15, activate the NRF2 signaling pathway in human renal cancer cells and primary mouse hepatocytes." (PMID 37693560, 2023).
emphysema (19 papers, 2005 to 2025). "EC-specific HIF-2α knockout mice exhibit reduced levels of hepatocyte growth factor (HGF), while human emphysema lungs also exhibit reduced expression of LEC-specific HIF-2α." (PMID 35053299, 2022). "Instead, the level of HGF, which protects against the development of emphysema, was significantly lower in IL-33−/− mice compared to WT mice following PPE instillation." (PMID 33992109, 2021). "Our previous studies demonstrated that HGF stimulates proliferation of respiratory epithelial cells, and ADSCs, via paracrine effects, improve an experimental rat model of pulmonary emphysema." (PMID 31281377, 2019). "Specifically this study sought to investigate the role for HGF in MSC cell mediated protection against elastase induced emphysema." (PMID 27922052, 2016). "In conclusion, using both loss-of-function and gain-of-function maneuvers, we show that HGF signaling is necessary for alveolar homeostasis in the developing lung and that augmentation of HGF signaling can improve airspace morphology in murine emphysema." (PMID 23459311, 2013). "We further showed that augmentation of HGF signaling in an established murine model of emphysema can improve airspace enlargement." (PMID 23459311, 2013). "Administration of recombinant HGF to tight-skin mice, an established genetic emphysema model, attenuated airspace enlargement and reduced oxidative stress." (PMID 23459311, 2013). "We have also found that pharmacologic augmentation with recombinant HGF in a murine model of emphysema results in both reduced oxidative stress in the airspace and improved airspace dimension." (PMID 23459311, 2013). "Investigators report both reduced and maintained HGF levels in the lungs of patients with COPD/emphysema." (PMID 23459311, 2013). "In our study, although HGF mRNA lung expression was similar in emphysema and non emphysema patients, a correlation was found between HGF mRNA and the deterioration of pulmonary function tests in emphysema patients." (PMID 16216128, 2005). "Reduced levels of HGF and VEGF may result in fewer capillaries and a reduced gas exchange capacity in the lung, which has been linked to the development of emphysema." (PMID 39859544, 2025). "It has been reported that VEGF and HGF protect against the development of emphysema." (PMID 33992109, 2021). "Furthermore, MSCs have been shown to inhibit proinflammatory response, cell apoptosis, and excessive protease expression by upregulating VEGF, TGF-β, and HGF in experimental emphysema." (PMID 34136481, 2021). "Activation of HGF/c-Met system, by promoting survival and proliferation of alveolar epithelial cells, may be a major determinant to trigger a reparative response in emphysema lung." (PMID 29731780, 2018). "Notably, the potent anti-apoptotic effect of MSC mediated against elastase induced emphysema has been validated both in vitro and in vivo with the importance of HGF signalling in the process established." (PMID 27922052, 2016). "We define here an important homeostatic role of HGF signaling in airspace formation, maintenance and regeneration suggesting that the HGF/c-Met pathway should be explored for airspace disorders such as bronchopulmonary dysplasia and emphysema." (PMID 23459311, 2013). "Given the multiple alveolar epithelial responses conferred by HGF signaling, we queried whether augmented HGF signaling might induce a protective or reparative response in murine models of emphysema." (PMID 23459311, 2013). "Reduced HGF expression and c-Met activation are evident in inbred mice with genetic emphysema." (PMID 23459311, 2013). "In emphysema patients, HGF mRNA correlated positively with total lung capacity (TLC) (Rho = 0.51, p = 0.04, n = 17) and negatively with forced expiratory volume in one second (FEV1) (Rho = -0.53, p = 0.03, n = 17) and FEV1/FVC (forced vital capacity) (Rho = -0.54, p = 0.03, n = 17)." (PMID 16216128, 2005).
emphysema (continued). "Using an informative battery of mouse models and cell lines, we show that hepatocyte growth factor is a determinant of alveolar formation and that the enhancement of hepatocyte growth factor signaling can both protect and repair the airspace from pathologic airspace enlargement or emphysema." (PMID 23459311, 2013). "Indeed, in view of the chronic lung injury observed in emphysema, one could expect an increase of HGF and KGF expression as observed in acute lung injury in rats and in humans." (PMID 16216128, 2005). "In support, emphysema-derived mesenchymal stromal cells expressed lower FGF-10 and hepatocyte growth factor (HGF) mRNA and HGF and decorin protein, indicating insufficient microenvironmental support for tissue regeneration." (PMID 35805139, 2022). "HGF is also a crucial cell factor for the lung repair in COPD, which reverses alveolar regeneration and restoration of pulmonary function affected by emphysema." (PMID 33489036, 2020). "Human bone marrow MSCs, administered early at the onset of the emphysema, exerted anti-inflammatory and antiapoptotic effects mediated in part through MSC production of HGF." (PMID 29731780, 2018). "We therefore evaluated the expression of HGF, KGF, and their receptors c-met and KGF-R in lung biopsies from patients with emphysema and from non-emphysema patients, according to their smoking status." (PMID 16216128, 2005). "HGF and KGF productions by lung fibroblasts from emphysema have been shown to be reduced when compared with controls." (PMID 16216128, 2005). "Both VEGF and HGF levels have been shown to be reduced in COPD patients, which may further contribute to emphysema in the lung parenchyma." (PMID 39014439, 2024). "This strong correlation between airflow obstruction and HGF mRNA in smokers suggests that the increase of HGF mRNA was not related to the presence of emphysema but rather to the degree of airflow obstruction." (PMID 16216128, 2005). "When all smokers were studied together (smokers with or without emphysema), again, significant correlations between HGF mRNA and FEV1 (Rho = -0.53, p = 0.009, n = 25), and FEV1/FVC (Rho = -0.49, p = 0.017, n = 25) were found." (PMID 16216128, 2005). "In this study, western blot analysis showed that HGF was only in the mature active form, both in lung biopsies from emphysema and non-emphysema patients." (PMID 16216128, 2005). "The correlation between airflow obstruction and HGF mRNA level was similarly observed when all smokers with or without emphysema were studied, suggesting that emphysema was not a main determinant of HGF mRNA level in the lung." (PMID 16216128, 2005). "Furthermore, since especially the expression of regenerative factors is of relevance with respect to therapeutic effects in emphysema, we performed targeted analysis on growth factors that play a critical role in alveolar epithelial regeneration based on literature, FGF7/KGF, FGF10 and HGF." (PMID 36681830, 2023). "Hepatocyte growth factor mRNA correlated negatively with FEV1 and the FEV1/FVC ratio both in emphysema patients and in smokers with or without emphysema." (PMID 16216128, 2005).